BHMT (betaine--homocysteine S-methyltransferase)
Description:
Involved in the regulation of homocysteine metabolism. Converts betaine and homocysteine to dimethylglycine and methionine, respectively. This reaction is also required for the irreversible oxidation of choline.
Synonyms: BHMT1; HEL-S-61p
Tractability: Small molecule: an approved drug acts on it; a structure with a bound ligand is known; a high-quality ligand is known; it has a binding pocket of medium quality; it belongs to a druggable protein family. PROTAC: its protein half-life has been measured; a small molecule that binds it is known.
Target class: Enzyme; Transferase
Gene: Protein-coding gene on chromosome 5 (79,111,807 to 79,132,289, forward strand). Ensembl gene ENSG00000145692.
Subcellular location: Cytoplasm, cytosol; Nucleus
Subcellular location (Human Protein Atlas): Cytosol
Pathways (Reactome):
Metabolism: Choline catabolism; Sulfur amino acid metabolism
Gene Ontology:
Molecular function: betaine-homocysteine S-methyltransferase activity; zinc ion binding; methyltransferase activity; S-methyltransferase activity
Biological process: 'de novo' L-methionine biosynthetic process; amino-acid betaine metabolic process; L-methionine salvage; S-adenosylmethionine metabolic process; amino-acid betaine catabolic process; modified amino acid metabolic process
Cellular component: extracellular exosome; cytosol; nucleus
Genetic constraint (gnomAD): Loss-of-function variants: 32 observed, 48.63 expected, observed/expected ratio (o/e) 0.66, 90% interval 0.5 to 0.88. The upper end of that interval is the gene's LOEUF score, 0.88, which puts it in group 3 of 6, group 1 being the genes least tolerant of losing a copy. Missense variants: 414 observed, 507.22 expected, observed/expected ratio (o/e) 0.82, 90% interval 0.75 to 0.88. Synonymous variants: 165 observed, 181.44 expected, observed/expected ratio (o/e) 0.91, 90% interval 0.8 to 1.03.
Homologues: Orthologues: chimpanzee BHMT2 (99% identical), macaque BHMT2 (99% identical), dog BHMT (95% identical), pig BHMT (95% identical), mouse Bhmt (94% identical), mouse Bhmt1b (94% identical), rat Bhmt (93% identical), guinea pig BHMT (90% identical), tropical clawed frog bhmt (83% identical), zebrafish bhmt (77% identical). Paralogues in human: BHMT2 (69% identical), MTR (28% identical), MTHFR (22% identical), UROD (14% identical).
Diseases named in the same sentence as BHMT in open-access papers:
BHMT is named in the same sentence as 67 diseases in open-access papers, as found by Europe PMC text mining. Sharing a sentence is not in itself a finding about the gene and the disease. The quoted sentences say what the papers report.
hyperhomocysteinemia (13 papers, 2006 to 2025). A serious metabolic condition caused by mutations in the MTHFR gene, medications, or nutritional deficiency. "The inhibition or deletion of BHMT causes hyperhomocysteinemia in mice." (PMID 25545100, 2014). "Such mtDNA hypermethylation in PCOS may be linked to hyperhomocysteinemia and subsequent significant upregulation of the one-carbon metabolic enzymes betaine homocysteine methyltransferase (BHMT) and glycine N-methyltransferase (GNMT) and the DNA methyltransferase DNMT1." (PMID 36498989, 2022). "The association of hyperhomocysteinemia with NTD risk implicates enzymes such as MTR, BHMT, and CBS that degrade homocysteine." (PMID 17035141, 2006). "BHMT is an important gene in the one-carbon metabolism pathway, and its downregulation could lead to hyperhomocysteinemia." (PMID 29232372, 2017). "Deficiency of the metabolic enzymes [e.g., betaine homocysteine methyltransferase (BHMT), cystathionine β-synthase (CBS), and cystathionine γ-lyase (CTH)] involved in these two pathways can lead to hyperhomocysteinemia." (PMID 34393786, 2021). "Further, to determine the relationship between 1-carbon metabolism, methylation, and hyperhomocysteinemia (HHcy), we measured DNMT, BHMT, and PEMT." (PMID 33708132, 2020). "The decrease in activity of betaine-homocysteine S-methyltransferase (BHMT) and cystathionine β-synthase (CBS) in GAA-induced hyperhomocysteinemia was recovered by supplementation with betaine or spinach." (PMID 25250392, 2014). "As one possibility, hepatic protein levels of BHMT and CBS may be saturated both in congenic and ExHC rats since both strains also develop homocysteinemia." (PMID 36810603, 2023).
hepatocellular carcinoma (11 papers, 2009 to 2025). A malignant tumor that arises from hepatocytes. "BHMT deficiency has been linked to hepatocellular carcinoma and fatty liver disease." (PMID 34490218, 2021). "A decline in BHMT expression has been observed in hepatocellular carcinoma (HCC), suggesting its potential as a marker for fatty liver disease and HCC onset." (PMID 39516467, 2024). "Changes in Hcy metabolism of non-genetic origin commonly result from decreased expression of key enzymes of this pathway, including BHMT as observed in hepatoma, cirrhosis or acute liver injury." (PMID 29924862, 2018). "To further examine the underlying mechanisms causing an upregulation of BHMT and a downregulation of CBS, we explored whether PPARα-activation by the agonist WY14,643 in rat hepatoma cells (Fao) can cause similar changes in gene expression in vitro as observed in the livers of obese mice." (PMID 23472083, 2013). "Noteworthy is that the health benefits of a concerted upregulation of BHMT-1, MAT-1, and GNMT by betaine treatment could counter their collective downregulation in human hepatocellular carcinoma." (PMID 19239903, 2009). "Our analysis of The Cancer Genome Atlas (TCGA) human Liver Hepatocellular Carcinoma (LIHC) dataset confirmed that key genes involved in SAA metabolism, including MAT1A, BHMT, CBS, CTH, and CDO1, are suppressed in HCC compared to normal liver." (PMID 32770044, 2020). "Interestingly, many enzymes involved in SAA metabolism, including MAT1A, GNMT, BHMT, and CBS, are reported to be downregulated in human liver tumors, particularly hepatocellular carcinoma (HCC), the most common and deadly form of liver cancer." (PMID 32770044, 2020).
Hepatic steatosis (9 papers, 2013 to 2026). Steatosis is a term used to denote lipid accumulation within hepatocytes. "The observed effects include alterations in CLD-associated levels of Plin2 and BHMT, both of which are functionally linked to fatty liver formation in mice." (PMID 23874434, 2013). "The genetic deletion of betaine-homocysteine S-methyltransferase (BHMT) was reported to perturb choline metabolism, inducing a decrease in phosphatidylcholine and resulting in hepatic steatosis." (PMID 37111122, 2023). "Additionally, it has been established that betaine-elicited inhibition of CHDH and activation of BHMT can collectively enhance catabolism, but decrease the synthesis of betaine in the liver in ApoE−/− mice with hepatic steatosis." (PMID 25010553, 2014).
diabetes (5 papers, 2014 to 2024). "Betaine homocysteine methyltransferase (BHMT) is an enzyme that catalyzes the synthesis of methionine from homocysteine and is associated with insulin resistance and diabetes." (PMID 37065737, 2023). "Furthermore, HHcy may also result from the increased Zn2+ loss observed in diabetes and alcoholism, as this cation is essential for BHMT activity." (PMID 29924862, 2018). "BHMT gene expression is altered in several diseases mainly concerning the liver (i.e. cirrhosis), but also in diabetes or Barret’s esophagus." (PMID 29924862, 2018). "In addition, it was shown that increased BHMT expression during diabetes induces the production of phosphatidylcholine along with involvement of phosphatidyl ethanolamine methylation." (PMID 25726699, 2015).
Cirrhosis (4 papers, 2018 to 2024). A chronic disorder of the liver in which liver tissue becomes scarred and is partially replaced by regenerative nodules and fibrotic tissue resulting in loss of liver function. "A dramatical reduction in the BHMT gene expression was observed in 90% of patients with hepatitis C virus-induced cirrhosis." (PMID 36982147, 2023). "We corroborated the expression levels of BHMT and CDO1 in various HCC cohorts and observed a marked suppression in HCC tumors compared to normal and cirrhosis samples across all independent cohorts examined." (PMID 39516467, 2024).
Obesity (4 papers, 2012 to 2024). Accumulation of substantial excess body fat. "Knockout mice lacking betaine-homocysteine methyltransferase (BHMT), one of the enzymes that remethylate homocysteine to methionine, have increased energy expenditure and insulin sensitivity, and are resistant to diet-induced obesity." (PMID 22984471, 2012).
spina bifida (4 papers, 2009 to 2023). A congenital neural tube defect in which vertebrae are not fully formed. "Mutations of the BHMT gene can significantly affect the metabolism of homocysteine, leading to several illnesses, including vascular disease, schizophrenia, and spina bifida." (PMID 36450445, 2023). "For example, Boyles and colleagues studied 28 SNPs in 11 folate-related genes and found that only BHMT (rs3733890) was associated with increased spina bifida risk." (PMID 19493349, 2009). "Haplotype reconstruction showed statistical evidence of nonrandom associations with TYMS, MTHFR, BHMT and MTR for spina bifida." (PMID 19493349, 2009). "Blocks for TYMS, MTHFR, BHMT, and MTR showed some evidence of nonrandom effects for spina bifida." (PMID 19493349, 2009).
steatosis (3 papers, 2024 to 2026). Increased lipid within the cytoplasm of cells. "Diet-induced steatosis reduced hepatic Pemt expression in control (Pparg-intact) mice, and the thiazolidinedione (TZD)-mediated activation of PPARγ in diet-induced obese control (Pparg-intact) mice reduced the expression of betaine homocysteine S-methyltransferase (Bhmt) and Cbs." (PMID 41929038, 2026).
acute kidney injury (2 papers, 2020 to 2025). Sudden and sustained deterioration of the kidney function characterized by decreased glomerular filtration rate, increased serum creatinine or oliguria. "ROS: reactive oxygen species; AKI: acute kidney injury; CPB: cardiopulmonary bypass; CABG: coronary artery bypass grafting; MACE: major adverse cardiovascular events; GSH: reduced glutathione; GSSG: oxidized glutathione; BHMT: betaine-homocysteine methyltransferase." (PMID 41367470, 2025).
coronary artery disease (2 papers, 2020 to 2023). "BHMT polymorphism may play a protective role in the risk of coronary heart disease and is associated with the incidence of uterine cervical cancer." (PMID 37633908, 2023). "first found that rs3733890 of the BHMT was associated with NSCL/P, and other studies also indicated its association with coronary artery disease and neural tube defects." (PMID 32124929, 2020).
Hearing impairment (2 papers, 2017 to 2022). A decreased magnitude of the sensory perception of sound. "They found that, in homozygous Cx30 mutations, a down-regulation of betaine homocysteine S-methyltransferase in the stria capillaries resulted in endothelial dysfunction and hearing loss." (PMID 36204137, 2022). "In Cx30−/− null mice hearing impairment was also associated with alterations in the stria vascularis, precisely down- and up-regulation of Betaine homocysteine methyltransferase (BHMT) and Ahcy expression, respectively, and increased Hcy immunostaining." (PMID 28487633, 2017).
hepatopathy (2 papers, 2010). "We proposed that this was due to the influence of hepatopathy on betaine-homocysteine S-methyltransferase (BHMT) expression levels in these mice." (PMID 20638879, 2010). "Significantly decreased BHMT expression as a consequence of the observed hepatopathy might explain why this treatment fails to significantly lower Hcy in the cbs (−/−) mice." (PMID 20638882, 2010).
ischemic stroke (2 papers, 2017 to 2021). A stroke disorder caused by obstruction of blood flow to the brain, due to thrombotic (local blood clot formation) or embolic (due to a blood clot or other material traveling from another site) event. "BHMT rs10037045 is reported to be a risk factor for ischemic stroke." (PMID 27822905, 2017).
type 2 diabetes (2 papers, 2013 to 2022). "In Zucker diabetic fatty rats representing a type 2 diabetes model and in a type 1 diabetes animal model with streptozotocin an impaired insulin secretion and signaling and an increased hepatic gene expression of CBS and BHMT representing the branch-point enzymes of C1-metabolism have been reported." (PMID 23472083, 2013).
atherosclerosis (1 paper, 2024). A disease characterized by the build-up of fatty material and calcium deposition in the arterial wall resulting in partial or complete occlusion of the arterial lumen. "BHMT is a thiomethyltransferase that contributes to the production of methionine from homocysteine and has a well-established relationship with atherosclerosis." (PMID 39199235, 2024).
cleft lip (1 paper, 2020). Congenital defect in the upper lip where the maxillary prominence fails to merge with the merged medial nasal prominences. "The four genetic missense variations 677C>T in MTHFR (rs1801133), 66A>G in MTRR (rs1801394), 776C>G in TCN2 (rs1801198), and 716 G>A in BHMT (rs3733890) have influence on protein function, and have been reported to be associated with cleft lip." (PMID 32124929, 2020). "Recently, many efforts have been made to find the genetic variants in folate pathway genes such as MTHFR (methylenetetrahydrofolate reductase), MTRR (Methionine synthase reductase), TCN2 (transcobalamin 2), and BHMT (betaine-homocysteine methyltransferase) and their susceptibility to cleft lip." (PMID 32124929, 2020).
congenital heart defects (1 paper, 2021). "Furthermore, genetic variants of SHMT1, BHMT, MGST1, MGMT, MTHFS, GNMT, and TRDMT1 were associated with an increased risk of congenital heart defects after prenatal antidepressant exposure." (PMID 33981330, 2021).
glioblastoma (1 paper, 2023). The most malignant astrocytic tumor (WHO grade IV). "In this study, we aimed to understand the relationship among SDC1, TGM2, FLOT1 and BHMT in modulating glioma autophagy and investigated their roles in regulating the radiosensitivity of glioblastoma by affecting the fusion of autophagosomes and lysosomes." (PMID 37441590, 2023).
glioma (1 paper, 2023). A benign or malignant brain and spinal cord tumor that arises from glial cells (astrocytes, oligodendrocytes, ependymal cells). "Kaplan-Meier curves showed that both FLOT1 and BHMT could mediate the worse prognosis of glioma patients." (PMID 37441590, 2023).
gout (1 paper, 2024). A condition characterized by painful swelling of the joints, which is caused by deposition of urate crystals. "To define NUMB rs374597310 and BHMT rs752243322 for causing hyperuricemia and gout, we investigated the functions of these two genes." (PMID 39433541, 2024).
hepatitis B virus infection (1 paper, 2023). A viral infection caused by the hepatitis B virus. "For example, genetic polymorphism rs585800 of BHMT was associated with the risk of hepatitis B virus infection." (PMID 36982147, 2023).
homocystinuria (1 paper, 2022). An autosomal recessive inherited metabolic disorder caused by mutations in the CBS, MTHFR, MTR, and MTRR genes. "Treatment for homocystinuria shows partial efficacy and involves methionine restriction and supplementation with vitamin B6, which is a cofactor for another enzyme, Betaine-homocysteine S-methyltransferase (BHMT), which can metabolize homocysteine." (PMID 35736461, 2022).
Hypercholesterolemia (1 paper, 2024). An increased concentration of cholesterol in the blood. "Taurine ameliorated hypercholesterolemia in rats fed a high cholesterol diet by directly enhancing the hepatic expression of BHMT and OATP2, which modulated the SHP and induced CYP7A1 and CYP8B1, thereby promoting cholesterol catabolism and lowering blood cholesterol levels." (PMID 39199235, 2024).
hypermethioninemia (1 paper, 2022). "This decrease in BHMT expression and activity has been linked to the hypermethioninemia observed in pnrCBS that could increase oxidative stress by reducing cysteine and glutathione production." (PMID 36376887, 2022).
liver cancer (1 paper, 2016). An epithelial or non-epithelial malignant neoplasm that arises from the liver. "Forty-seven primary liver cancer patients were genotyped for ten polymorphisms: DHFR 19bp ins/del, TS 2rpt-3rpt, MTHFD1 1958G>A, MTHFR 677C>T, MTR 2756A>G, MTRR 66A>G, RFC1 80G>A, SHMT1 1420C>T, BHMT 716 A>G, TC II 776C>G." (PMID 27936032, 2016).
metabolic myopathies (1 paper, 2014). "VPA alters the expression of PEBP1, BHMT, MYL1, ALB and FLNC that are closely related with metabolic myopathies, myogenesis, albumin gene expression, and haemolytic anemia." (PMID 25551574, 2014).
pneumonia (1 paper, 2019). An acute, acute and chronic, or chronic inflammation focally or diffusely affecting the lung parenchyma, caused by an infection in one or both of the lungs (by bacteria, viruses, fungi, or mycoplasma.). "Moreover, the expression of eight DEPs (PECAM1, PGLYRP1, AHCY, BHMT, EML3, ICOSLG, IGHV3‐23 and RTN4RL2) in normal and pneumonia groups (two patients) was quite different from that in the KD group." (PMID 30761252, 2019). "Moreover, the expression of eight of these 30 DEPs (PECAM1, PGLYRP1, AHCY, BHMT, EML3, ICOSLG, IGHV3‐23 and RTN4RL2) clustered normal and pneumonia samples into one group and clustered KD samples into another group, which heightens the importance of these eight DEPs in KD." (PMID 30761252, 2019).
tyrosinemia type I (1 paper, 2018). "Hence, interaction of HPD and BHMT may result in a crosstalk between both pathways in order to control methionine levels, which may otherwise increase in parallel with fumaryl acetoacetate concentrations as observed in tyrosinemia type I." (PMID 29924862, 2018).
ventricular septal defect (1 paper, 2022). The presence of a defect (opening) in the septum that separates the two ventricles of the heart. "This study attempted to learn the association between maternal betaine-homocysteine methyltransferase (BHMT) gene polymorphisms, maternal dietary habits, and their interactions with the risk of ventricular septal defects (VSD) in offspring." (PMID 35956270, 2022).
virus infections (1 paper, 2023). "However, the molecular mechanisms through which BHMT regulates PEDV replication and whether BHMT functions in other virus infections such as the transmissible gastroenteritis virus and porcine Delta coronavirus remain to be further explored." (PMID 36982147, 2023).
Zinc deficiency (1 paper, 2020). A deficiency of the essential metal Zinc; an essential cofactor for many enzymes. "Since two enzymes in homocysteine metabolism, methionine synthase (MS) and betaine homocysteine methyltransferase (BHMT) are zinc-dependent, a zinc deficiency is a major factor in the increase in homocysteine concentration." (PMID 33228216, 2020).
tumor (9 papers, 2017 to 2024). "Differential expression analysis of TCGA-LIHC tumor tissues and adjacent normal tissues revealed that the expression differences of TMEM45A, S100A10, SERPINA12, BHMT, CFHR3, RPL8, and STMN1 all exceed a 2-fold change." (PMID 39176099, 2024). "SPP1, CRYAB, NNMT and HILPDA were highly expressed in tumour cells (ccRCC1); GSTA2, BHMT and ADSSL1 were highly expressed in tumour cells 1 (ccRCC2); and HIF1A-AS2, DNAH11 and EGOT were highly differentially expressed in tumour cells 2 (ccRCC2)." (PMID 34168986, 2021).